VASH2 (vasohibin 2)
Diseases named in the same sentence as VASH2 in open-access papers (continued):
Sharing a sentence is not in itself a finding about the gene and the disease.
pancreatic cancer (continued). "Immunohistochemical staining for VASH2 was performed on 102 human pancreatic cancer samples." (PMID 28327155, 2017). "To further assess the effect of VASH2 on the sensitivity of pancreatic cancer cells to chemotherapy, we generated human pancreatic cancer cells overexpressing VASH2 (PANC-1-VASH2) and in which VASH2 had been knocked down using a small hairpin RNA (SW1990-shVASH2)." (PMID 28327155, 2017). "Pancreatic cancer cell line models exhibiting overexpression or knockdown of VASH2 were generated." (PMID 28327155, 2017). "The proportion of specimens with middle/strong VASH2 staining was significantly lower in vessel cancerous embolus negative pancreatic cancer tissues than in vessel cancerous embolus positive pancreatic cancer tissues (47/89 [52.8%] vs. 11/13 [84.6%], respectively; P = 0.031)." (PMID 28327155, 2017). "Survival analysis indicated that tumors that were negative/weak for VASH2 staining were more sensitive to gemcitabine chemotherapy than tumors exhibiting middle/strong VASH2 staining, indicating that VASH2 may be related with gemcitabine sensitivity in pancreatic cancer." (PMID 28327155, 2017). "Therefore, VASH2 may represent a novel target for anti-chemoresistance therapy in the gemcitabine chemotherapy of pancreatic cancer; VASH2 may also be used as a marker to guide the gemcitabine chemotherapy of pancreatic cancer." (PMID 28327155, 2017). "Knockdown of Vasohibin-2 (VASH2), an endothelium-derived angiogenesis inhibitor, in murine pancreatic cancer cells downregulates NF-ĸB signaling, which results in decreased infiltration of CD11b+ Ly6G+ G-MDSC mediated by low Cxcl2 and Cxcl5." (PMID 34439836, 2021). "VASH2 increased the expression of ZEB1/2 in pancreatic tumors through activation of the SHH pathway, which both facilitated the EMT process and increased the resistance of pancreatic tumors to gemcitabine chemotherapy." (PMID 37821528, 2023). "Here, we found that VASH2 is expressed at high levels in human pancreatic cancer cells and acts as a gemcitabine-resistance factor, and the expression of RRM2 could be upregulated by VASH2 in a JUN-dependent manner." (PMID 28327155, 2017). "We further detected the expression of VASH2 protein in pancreatic cancer cell lines (Miapaca‐2, Capan‐1, CFPAC‐1, PANC‐1, SW1990, HPAC, and BxPc‐3) by Western blot, which revealed that PANC‐1 cells had higher expression of VASH2, while BxPc‐3 cells displayed lower VASH2 expression." (PMID 30318866, 2018).
gastric cancer (5 papers, 2014 to 2023). A primary or metastatic malignant neoplasm involving the stomach. "In various gastric cancer cell lines, the mRNA expressions of VASH2 has been reported to be inconsistent with that of VEGF." (PMID 32604722, 2020). "In addition, another study demonstrated that VASH2 expression did not correlate with VEGF-A level in gastric cancer." (PMID 29641565, 2018).
esophageal cancer (3 papers, 2020 to 2022). A primary or metastatic malignant neoplasm involving the esophagus. "In addition, VASH2 expression has been associated with cancer progression and poor prognosis in various malignancies, such as pancreatic and esophageal cancers." (PMID 32604722, 2020).
serous ovarian adenocarcinoma (3 papers, 2013 to 2014). "In ovarian serous adenocarcinoma cells, the expression of VASH2 was inversely correlated with that of miR-200b, which represses the expression of ZEB1 and ZEB2, the products of which are key to epithelial-to-mesenchymal transition." (PMID 23426782, 2013). "Recently, we demonstrated that VASH2 contributes to the development of tumor growth and peritoneal dissemination by promoting angiogenesis in human ovarian serous adenocarcinoma." (PMID 23426782, 2013).
colon carcinoma (2 papers, 2014 to 2015). "Tumors used to examine endogenous VASH2 (derived from CMT93 colon carcinomas) were less vascularized in Vash2-/- mice and were more regular than those seen in wild-type (WT) mice." (PMID 24885408, 2014). "However, the VASH2 expression patterns in colon cancer cell lines are different from that of VASH1 expression." (PMID 25797264, 2015).
diabetes (2 papers, 2018 to 2020). "Diabetes-induced glomerular hypertrophy and mesangial expansion were significantly improved in VASH2-deficient diabetic mice." (PMID 29641565, 2018). "One of the most notable findings in this study was the prevention of diabetes-induced urine albumin excretion in VASH2-deficient mice." (PMID 29641565, 2018). "Although diabetes led to marked increase in UAE in WT mice, it was significantly and almost entirely prevented in VASH2-deficient diabetic mice." (PMID 29641565, 2018). "Accordingly, diabetes-induced increase in glomerular volume and reduction in glomerular slit-diaphragm density were significantly improved in VASH2 knockout mice." (PMID 29641565, 2018). "However, VASH2 deficiency did not affect VEGF-A level in both non-diabetic and diabetic conditions, whereas increased VEGFR-2 expression induced by diabetes was suppressed in diabetic VASH2-deficient mice, suggesting that VASH2 might enhance VEGF signaling in endothelial cells." (PMID 29641565, 2018). "Vasohibin-2 is recently shown to be in diabetes-induced glomerular alterations." (PMID 32982792, 2020). "Therefore, VASH2 might accelerate diabetes-induced transformation of mesangial cells to fibroblast-like cells." (PMID 29641565, 2018). "Elevated level of renal VEGF-A induced by diabetes in WT mice was not affected by VASH2 deficiency." (PMID 29641565, 2018).
diabetic nephropathy (2 papers, 2018 to 2020). "In a diabetic nephropathy mouse model, VASH2 deficiency ameliorated albuminuria and glomerular injury." (PMID 32604722, 2020). "In the present study, we have demonstrated the improvement of diabetic nephropathy in VASH2-deficient mice, and the inhibition of high glucose-induced extracellular matrix (ECM) protein production in cultured mesangial cells with suppressed VASH2 expression." (PMID 29641565, 2018). "Herein, we investigated the pathogenic roles of VASH2 in diabetic nephropathy using VAHS2-deficient mice." (PMID 29641565, 2018). "In our recent report, we showed that renal VASH2 expression was significantly increased in a diabetic nephropathy mouse model." (PMID 32604722, 2020). "Considering up-regulation of VASH2 in cultured mesangial cells treated with high glucose concentration, renal VASH2 should play significant roles in diabetic nephropathy." (PMID 29641565, 2018). "Because VEGF inhibition often leads to proteinuria and renal thrombotic microangiopathy, VASH2 is likely to be a superior target for anti-angiogenic therapy in diabetic nephropathy, similar to cancers." (PMID 29641565, 2018). "Therefore, VASH2 expression in mesangial cells may accelerate glomerular extracellular matrix production observed in diabetic nephropathy." (PMID 29641565, 2018). "Therefore, VASH2 is likely to represent a promising therapeutic target for diabetic nephropathy." (PMID 29641565, 2018). "In addition, given that VASH2 knockout mice have no obvious phenotype, VASH2-targeting therapy for diabetic nephropathy is unlikely to result in the glomerular endothelial injury that was observed in anti-VEGF antibody-treated patients." (PMID 29641565, 2018).
endometrial cancer (2 papers, 2013 to 2020). Primary or metastatic malignant neoplasm involving the endometrium (mucous membrane that lines the endometrial cavity). "To clarify the function of VASH2 in endometrial cancer, we performed a loss-of-function experiment by knocking down VASH2 expression." (PMID 23426782, 2013). "In summary, VASH2 contributes to the development of endometrial cancer by regulating angiogenesis through paracrine effects." (PMID 23426782, 2013). "VASH2 mRNA expression was considerably higher in several human endometrial cancer cell lines than in the HUVECs." (PMID 23426782, 2013). "To examine the possible involvement of VASH2 in endometrial cancer, we analyzed human endometrial cancer cell lines by quantitative RT-PCR." (PMID 23426782, 2013). "In the present study, we examined the correlation between VASH2 and endometrial cancer cell for the first time." (PMID 23426782, 2013). "VASH2 was expressed in human endometrial cancer cell lines, and the specific knockdown of VASH2 from the endometrial cancer cell line, HEC50B, significantly inhibited tumor growth by decreasing tumor angiogenesis." (PMID 23426782, 2013). "In this study, we used a short hairpin RNA (shRNA) vector to silence VASH2 expression in a VASH2-expressing endometrial cancer cell line, to further elucidate the relationship between VASH2 expression and endometrial cancer progression." (PMID 23426782, 2013). "We used HEC50B, an endometrial cancer cell line with high VASH2 expression, for the following experiments." (PMID 23426782, 2013). "Taking its stimulatory effect on angiogenesis into account, VASH2 may be a novel molecular target for the treatment of endometrial cancer." (PMID 23426782, 2013). "Moreover, we investigated the function of VASH2 in endometrial cancer angiogenesis to develop a VASH2-targeted anti-angiogenic molecular therapy for endometrial cancer." (PMID 23426782, 2013). "Consequently, VASH2 may be considered to be a novel molecular target for endometrial cancer therapy." (PMID 23426782, 2013). "However, the specific role of VASH2 in endometrial cancer remains unknown." (PMID 23426782, 2013). "Using quantitative reverse transcription-polymerase chain reaction (RT-PCR), we found that VASH2 was overexpressed in several human endometrial cancer cell lines, including the HEC50B cell line, which we used to further examine the role of VASH2." (PMID 23426782, 2013).
liver cancer (2 papers, 2014 to 2017). An epithelial or non-epithelial malignant neoplasm that arises from the liver. "To further investigate the efficacy and mechanism of the combination of VASH2 with anti-cancer drugs in liver cancer cells, we stably built VASH2 overexpression and knockdown cell lines." (PMID 24595063, 2014).
non-small cell lung carcinoma (2 papers, 2023 to 2024). A group of at least three distinct histological types of lung cancer, including non-small cell squamous cell carcinoma, adenocarcinoma, and large cell carcinoma. "In addition, in a study on non-small cell lung cancer, researchers found that VASH2 promoted tumor cell proliferation and resistance to adriamycin through the AKT signaling pathway." (PMID 37821528, 2023).
adenoma (1 paper, 2014). A neoplasm arising from the epithelium. "Strong X-gal staining was observed in the crypt of the normal small intestine and in tumor cells in adenoma or adenocarcinoma in ApcMin/+/Vash2-/- mice." (PMID 24885408, 2014). "VASH2 protein was detected around tumor blood vessels in late-stage adenoma and adenocarcinoma in ApcMin/+ mice." (PMID 24885408, 2014). "Histologically, all polyps in ApcMin/+/Vash2-/- mice were adenomas or adenocarcinomas, similar to those in ApcMin/+ mice." (PMID 24885408, 2014). "In our study, VASH2 was mainly expressed by late stage adenoma and spontaneous adenocarcinoma cells around tumor vessels in ApcMin/+ mice." (PMID 24885408, 2014). "The up-regulation of VASH2 in adenoma may induce the observed changes in vascular architecture, similar to those observed in malignant tumors." (PMID 24885408, 2014). "The effects of VASH2 on adenoma growth and progression to carcinomas were also examined by cross-breeding mice with a complete absence of Vash2 expression (Vash2-/- mice) with ApcMin/+ mice." (PMID 24885408, 2014). "Moreover, VASH2 protein was detected around tumor blood vessels in late-stage adenomas and adenocarcinomas, while early-stage adenomas stained negative for VASH2 in ApcMin/+ mice." (PMID 24885408, 2014). "If new anti-vascular agents such as anti-VASH2 neutralizing antibodies could be developed to suppress changes in local vascular networks, the intestinal epithelium may not become malignant during the adenoma-carcinoma sequence." (PMID 24885408, 2014). "In addition, a novel angiogenic factor, vasohibin-2 (VASH2) protein, was detected around tumor blood vessels in late-stage adenomas and adenocarcinomas, but was absent from early-stage adenomas in ApcMin/+ mice." (PMID 24885408, 2014).
Cerebral ischemia (1 paper, 2021). Restriction of arterial blood supply to the brain associated with insufficient oxygenation to support the metabolic requirements of the tissue. "Vash-2, in contrast, enhances intratumoral angiogenesis, and its function in the context of cerebral ischemia injury remains to be clarified." (PMID 34287581, 2021).
head and neck squamous cell carcinoma (1 paper, 2025). A squamous cell carcinoma that arises from any of the following anatomic sites: lip and oral cavity, nasal cavity, paranasal sinuses, pharynx, larynx, and salivary glands. "VASH1 and VASH2 play contrasting roles in angiogenesis, a critical process driving tumor growth and metastasis in head and neck squamous cell carcinoma (HNSCC)." (PMID 40483461, 2025).
Hypertension (1 paper, 2013). The presence of chronic increased pressure in the systemic arterial system. "As a VEGF-independent and EC-extrinsic angiogenesis regulator, VASH2 is considered to be a novel target for anti-angiogenic therapy that enables the toxic side effects of anti-VEGF therapy, such as hypertension and proteinuria, to be avoided." (PMID 23426782, 2013).
intestinal polyposis (1 paper, 2014). "To determine the relationship between VASH2 suppression and intestinal polyposis, we assessed Vash2 mRNA levels in the intestinal mucosa and polyps." (PMID 24885408, 2014).
Intestinal tumors (1 paper, 2014). "Intestinal tumors from ApcMin/+ mice and ApcMin/+/Vash2-/- mice were removed and either frozen or epon-embedded for subsequent analyses." (PMID 24885408, 2014).
malignant neoplasms of the pancreas (1 paper, 2022). "The association between the location of the tumor in the pancreas and the concentration of VASH-1 and VASH-2 was also found in other malignant neoplasms of the pancreas." (PMID 35372578, 2022).
medulloblastoma (1 paper, 2023). A malignant, invasive embryonal neoplasm arising from the cerebellum. "The results of the multifactorial analysis showed that positive expression of VASH2 was associated with medulloblastoma molecular subtype (SHH type), site of tumor development (four ventricles), and gender (male), P < 0.05." (PMID 37821528, 2023). "This suggests that it is involved in the progression of pediatric medulloblastoma, and VASH2 is expected to be a diagnostic and therapeutic target for SHH-type pediatric medulloblastoma." (PMID 37821528, 2023). "Due to the large number of lost cases, the final sample size included in this study was 47 cases, and exploring the prognostic relationship between VASH2 and medulloblastoma still needs to be investigated in a large sample cohort in the future." (PMID 37821528, 2023). "In the present study, we found that modulation of VASH2 overexpression in SHH medulloblastoma cell lines DAOY increased the S phase in the Daoy cell cycle, whereas knockdown of VASH2 shortened the S phase in the Daoy cell cycle." (PMID 37821528, 2023). "VASH2 was expressed to varying degrees in the tissues of all three subtypes of childhood medulloblastoma." (PMID 37821528, 2023). "Subsequently, we performed VASH2 regulatory modeling experiments in SHH medulloblastoma cell lines DAOY with two medulloblastoma datasets GSE30074 and GSE202043 (medulloblastoma samples), and their corresponding clinical information obtained from the GEO database." (PMID 37821528, 2023). "In this study, we examined the expression level of VASH2 in pediatric medulloblastoma tissues by immunohistochemistry and found that the positive expression rate of VASH2 was closely related to the molecular typing of medulloblastoma." (PMID 37821528, 2023). "The correlation between VASH2 and molecular typing of medulloblastoma was analyzed." (PMID 37821528, 2023). "The expression of Bcl2 and Caspase3 in the VASH2-OE group was the most significant difference compared to the other two groups (P < 0.05), and the results showed that VASH2 may be a key factor affecting apoptosis in SHH medulloblastoma cell-lines DAOY." (PMID 37821528, 2023). "Flow cytometric cycle analysis showed that VASH2 overexpression increased the S phase in the Daoy cell cycle, while VASH2 knockdown decreased the S phase in the SHH medulloblastoma cell lines DAOY cell cycle." (PMID 37821528, 2023). "Flow cytometry was used to analyze the alteration of the SHH medulloblastoma cell lines DAOY cell cycle by overexpression and silencing of the VASH2 gene." (PMID 37821528, 2023). "The results suggest that overexpression of VASH2 in SHH medulloblastoma cell lines DAOY promotes medulloblast proliferation, and VASH2 knockdown inhibited the proliferation of myeloblasts." (PMID 37821528, 2023). "We used Transwell chambers to detect the effects of VASH2 overexpression and VASH2 silencing on the migration and invasion ability of SHH medulloblastoma cell lines DAOY." (PMID 37821528, 2023). "VASH2 was positive in 20 cases of SHH-type medulloblastoma and negative in 9 cases, with a positive rate of 68.97%, and VASH2 was positive in 3 cases of non-SHH/WNT-type medulloblastoma and negative in 7 cases, with a positive rate of 30%." (PMID 37821528, 2023). "The results of the assay showed no statistical difference in the proliferation ability of the three groups, (P > 0.05) thus it is clear that modulation of VASH2 does not affect the proliferation ability of SHH medulloblastoma cell lines DAOY." (PMID 37821528, 2023). "The results showed that Smad2 + 3, Smad4, Bcl2, and Caspase3 expression was changed in SHH medulloblastoma cell lines DAOY regardless of overexpression or knockdown of VASH2, indicating that VASH2 expression in myeloblasts may be mediated by affecting downstream indicators of TGFβ pathway." (PMID 37821528, 2023).
myocardial infarction (1 paper, 2024). Gross necrosis of the myocardium, as a result of interruption of the blood supply to the area, as in coronary thrombosis. "The mechanistic studies confirmed that miR199a-5p could protect the heart from myocardial infarction injury by controlling the AGTR1/NOX4 and MARK4/VASH2/dTyr-tub pathways." (PMID 38956062, 2024).
osteoarthritis (1 paper, 2021). A noninflammatory degenerative joint disease occurring chiefly in older persons, characterized by degeneration of the articular cartilage, hypertrophy of bone at the margins and changes in the synovial membrane. "It is possible that the association with the variant in the VASH2 gene reflects the osteoarthritis aspect of the FCI score (reflected in the higher grades)." (PMID 34474664, 2021).
pancreatic adenocarcinoma (1 paper, 2022). "In the case of pancreatic adenocarcinoma, based on the analysis of tissue models in mice, high VASH-2 concentration has been shown to be associated with the metastatic process and a worse prognosis." (PMID 35372578, 2022).
renal fibrosis (1 paper, 2020). A final common manifestation of a wide variety of chronic kidney diseases characterized by glomerulosclerosis and tubulointerstitial fibrosis. "Considering the pathological roles of EMT in renal fibrosis, sustained expression of VASH2 in renal tubular epithelial cells after I/R injury may accelerate post-AKI interstitial fibrosis." (PMID 32604722, 2020).
type 1 diabetes (1 paper, 2018). "First, we evaluated the role of endogenous VASH2 in a type 1 diabetes model, and thus, the use of type 2 diabetes model should be considered in the future." (PMID 29641565, 2018). "The type 1 diabetes model was induced by intraperitoneal injections of streptozotocin in VASH2 homozygous knockout (VASH2LacZ/LacZ) or wild-type mice." (PMID 29641565, 2018).